MTOR (mechanistic target of rapamycin kinase)
Diseases named in the same sentence as MTOR in open-access papers (continued):
Sharing a sentence is not in itself a finding about the gene and the disease.
cyst (continued). "The results obtained here showed that GA strongly inhibited MDCK cyst enlargement by inhibiting MDCK and Pkd1 mutant cell proliferation, which could suppress phosphorylation of the ERK1/2 and mTOR/S6K signaling pathways, as well as activate AMP-activated protein kinase." (PMID 35744960, 2022). "Although rapamycin has shown clear benefits in preclinical experiments and clinical trials for ADPKD, the precise molecular mechanism by which PC2 regulates cell growth via mTOR and how rapamycin inhibits cyst growth and epithelial‐cell proliferation have not been clarified." (PMID 28244683, 2017). "The adenylyl cyclase activator forskolin was used as a positive control to induce cyst growth and compared with compound C1, a curcumin derivative that has been shown to directly bind to Tfeb and induce its nuclear translocation independent of mTOR pathway modulation." (PMID 36794754, 2023). "We show that inhibition of several targets, including aurora kinase, CDK, Chk, IGF-1R, Syk, and mTOR, but, surprisingly, not PI3K, prevented forskolin-induced cyst swelling." (PMID 28644734, 2017). "Together, these findings indicate that mTOR, but not PI3K, plays a role in driving forskolin-induced cyst swelling in this model." (PMID 28644734, 2017). "We also showed a lack of synergy between PI3K and mTOR inhibitors buparlisib and torin 1, indicating that PI3K does not play a role in cyst growth in this in vitro assay for cyst growth." (PMID 28644734, 2017). "mTOR signalling has been identified as a core dysregulated pathway in ADPKD, and while mTOR inhibitors slow cyst growth in mice, clinical studies in humans have not yielded similar results and have demonstrated significant side effects, limiting the tolerated dose." (PMID 40722835, 2025). "Currently, it appears that research on the use of mTOR in ADPKD, despite a solid theoretical foundation and a proven mechanism of action, has not demonstrated sufficient effectiveness in limiting cyst growth and will not be continued because of the emergence of better therapeutic options." (PMID 39339816, 2024). "We therefore considered whether PI3K, which is aberrantly active in PKD,22,23 was not involved in cyst growth in our model, or whether the PI3K inhibition could exert synergistic effects together with mTOR inhibitors." (PMID 28644734, 2017).
colitis (101 papers, 2015 to 2025). Inflammation of the colon. "On the other hand, activation of mTOR signaling can cause colitis, and overproduction of IL-6 can inhibit Treg proliferation." (PMID 35237152, 2022). "During colitis, loss of both mTOR complexes in colonic ILC3s results in the reduced production of inflammatory mediators, recruitment of neutrophils and immunopathology." (PMID 34341503, 2021). "In this way, targeting mTOR signaling in epithelial cells can effectively reduce the incidence of acute colitis complications caused by clinical glucocorticoids in the treatment of other acute severe inflammatory diseases." (PMID 32290362, 2020). "While mTOR has been linked to mouse colitis through the effect of rapamycin, the pathway was presumed to promote inflammation by affecting T helper cell proliferation and polarization, and the role of epithelial mTOR was not explored." (PMID 29596476, 2018). "Notably, loss of mTOR signaling in dendritic cells impairs IL-10 production by conventional type 2 dendritic cells, heightening susceptibility to colitis." (PMID 40565877, 2025). "Altogether, the increased mTOR activity caused by TSC1 deficiency in macrophages might contribute to the accelerated DSS-induced colitis in TSC1cKO mice and high expression of IL-17A, IL-17F, and IFN-γ in macrophages." (PMID 36465179, 2022). "Hence the reduced expression of such neutrophil-mobilizing cytokines by ILC3s in mTOR-deficient mice might be responsible for the reduced infiltration with neutrophils during α-CD40-induced colitis." (PMID 34341503, 2021). "In the colon tissue of mice with DSS-induced colitis, the expressions of P62, mTOR, and p-mTOR increased, while ATG16L1 and LC3II/I decreased." (PMID 40534879, 2025). "A previous study has shown that NLRP3 is a direct binding partner for the autophagy inhibitor mTOR and in colitis mice, hypoxia ameliorated intestinal inflammation by reducing NLRP3-mTOR binding and thus activating autophagy." (PMID 39936902, 2025). "In the present study, the PTX group exhibited a significant increase in colonic AMPK expression and a significant decrease in colonic expression of NLRP3 and mTOR when compared to the colitis group." (PMID 40387460, 2025). "We further found that in A. shahii As360-treated colitis mice, the expression of mtor and Nlrp3 genes was reduced while the expression of mTOR inhibitor gene Ddit4 was increased." (PMID 39936902, 2025). "The colitis group showed a significant increase in both colon mTOR content and NLRP3 gene expression, with 3.61‐fold (F = 528.4, p < 0.0001) and 3.68‐fold (F = 66.14, p < 0.0001) increases, respectively, compared to the normal control group." (PMID 40387460, 2025). "In murine DSS-induced colitis, increased mTOR activity correlates with epithelial proliferation in inflamed areas." (PMID 40565877, 2025). "Preclinical studies in animal models, such as EAE and DSS-induced colitis, have consistently demonstrated the efficacy of targeting metabolic nodes like mTOR, AMPK, HIF-1α, and PKM2 in rebalancing Th17/Treg responses." (PMID 41476956, 2025). "Experimental colitis and oxidative stress were significantly reduced in vivo by the pharmacological injection of mTOR inhibitors and autophagy stimulators." (PMID 40534879, 2025). "Another study found that the colitis animals exhibit significantly increased autophagy-related proteins like mTOR, P62, and p-MTOR in IHC but substantially reduced LC3B levels." (PMID 40534879, 2025). "Studies have shown that the administration of Baitouweng decoction can repair the intestinal epithelial barrier in colitis by regulating the AMPK/mTOR mediated autophagy pathway." (PMID 40532039, 2025). "Another study showed that resveratrol alleviated DSS-induced colitis by down-regulating protein abundance involved in autophagy and up-regulating levels of phosphorylated mTOR and SIRT1." (PMID 37298531, 2023).
colitis (continued). "IL-10 prevents colitis by eliminating dysfunctional mitochondria and inhibiting mTOR signaling and inflammatory vesicle activation in macrophages." (PMID 38029081, 2023). "As such, IL‐10 signaling is required for intestinal macrophages to prevent pro‐inflammatory exacerbation during DSS‐induced colitis through inhibition of mTOR signaling which controls macrophage pro‐inflammatory activity." (PMID 36795015, 2023). "Autophagy is negatively regulated by upstream mTOR, and the pharmacological effects of mTOR inhibitors and autophagy stimulators significantly improve experimental colitis and oxidative stress in vivo." (PMID 37168865, 2023). "Previous results have shown that the colon of colitis animal models have a high degree of phosphorylation of S6 suggesting that mTOR is involved in the disease, with inhibition of mTOR attenuating DSS induced colitis." (PMID 35499706, 2022). "LCA and DCA inhibit the production of proinflammatory cytokines by human peripheral blood-derived macrophages via the TGR5 receptor, and DCA produced by gut microbes inhibits the mTOR signaling pathway and alleviates C. jejuni-induced colitis." (PMID 36713373, 2022). "In conclusion, BMSCs improve TNBS-induced colitis by expressing PD-L1, and its mechanism is mainly related to the inhibition of the Akt/mTOR pathway which can induce Treg differentiation." (PMID 36261682, 2022). "This study provides additional insights into alterations associated with DSS/AOM-induced colitis and associates PI3K-Akt-mTOR, sphingolipid-signaling and lipoarabinomannan biosynthetic pathways in mouse DSS/AOM-induced colitis." (PMID 34359585, 2021). "Using mice specifically defective for either mTORC1 or mTORC2 in ILC3s, we show that both mTOR complexes regulate the maintenance of ILC3s at steady state and pathological immune response during colitis." (PMID 34341503, 2021). "The mTOR inhibitor AZD8055 (ATP-competitive mTOR inhibitor) alleviates experimental colitis in mice." (PMID 34588980, 2021). "Previous studies have shown that mTOR is critical for colitis and that p-S6 (an mTOR downstream target) is significantly upregulated in Dex-treated CD45- colonic epithelial cells." (PMID 32290362, 2020). "Inhibition of PI3K/Akt/mTOR can also inhibit colonic inflammation in proinflammatory factor-induced colonic diseases and colitis." (PMID 31281227, 2019). "We found that hyperactivated mammalian target of rapamycin (mTOR) signaling interferes with the proper differentiation of epithelial cells, which promotes colitis by altering the epithelial inflammatory cytokine secretion in the colon." (PMID 29596476, 2018). "Aloperine regulates the inflammatory response in colitis through inhibiting the PI3K/Akt/mTOR signaling pathway in a protein phosphatase 2A-dependent manner." (PMID 29710817, 2018). "In order to investigate a potential role for mTOR in driving colonic inflammation by affecting epithelial homeostasis, we tested the effects of the mTOR inhibitor rapamycin on colitis induced in the TCT model." (PMID 29596476, 2018). "The identification of mTOR signaling as a mediator of colitis in the TCT model provided an entryway to study the cellular mechanisms controlling intestinal homeostasis." (PMID 29596476, 2018). "In animals with colitis, by contrast, we detected strong p-S6 throughout the colonic epithelium, suggesting that the increased mTOR signal that we detected derives primarily from ectopic activation in epithelial cells." (PMID 29596476, 2018). "Using dimensionality reduction algorithms, we predicted mammalian target of rapamycin (mTOR) signaling as a driver of colitis." (PMID 29596476, 2018). "In conclusion, aloperine regulates inflammatory responses in colitis by inhibiting the PI3K/Akt/mTOR signaling in a PP2A-dependent manner." (PMID 29056830, 2017). "Administration of rapamycin during AA diet consumption prevented colitis exacerbation suggesting that mTOR activation was involved in the effects triggered by the AA diet." (PMID 29209321, 2017).
colitis (continued). "To confirm that mTOR activation by amino acid containing diet (AA diet) was involved in exacerbation of colitis, we treated AA-diet-fed mice daily with the mTOR inhibitor rapamycin during diet consumption and previously to colitis induction by DSS." (PMID 29209321, 2017). "Blockage of mTOR activation by treatment with rapamycin during AA diet consumption prevented colitis exacerbation suggesting this cellular sensor complex was involved in the effect mediate by the AA diet." (PMID 29209321, 2017). "Because PTEN controls PI3K/AKT/mTOR signaling and patients with PHTS present with significant changes in the T- and B-cell compartment associated with autoimmunity, colitis, and lymphoid hyperplasia, we expected abnormalities in the Treg cell compartment." (PMID 27477328, 2017). "Here we show that hypoxia ameliorates inflammation during the development of colitis by modulating autophagy and mammalian target of rapamycin (mTOR)/NLRP3 pathway." (PMID 28740109, 2017). "Aloperine regulates the inflammatory responses in colitis by inhibiting the PI3K/Akt/mTOR signaling in a PP2A-dependent manner." (PMID 29056830, 2017). "To address the putative role mTOR activation in the inflammatory effects triggered by the AA diet, we used rapamycin during AA diet consumption prior to colitis induction." (PMID 29209321, 2017). "Several studies have demonstrated that blockade of mTOR activation by inhibitors such as rapamycin and everolimus reduces experimentally induced colitis." (PMID 29209321, 2017). "It activates ERβ, and therefore inhibits mTORC1 activation and destroys mTOR-raptor interaction through binding to raptor, thus leading to a down-regulation of Th17 cell differentiation and amelioration of colitis." (PMID 27863380, 2016). "In this study, we found that ATP-competitive dual mTOR inhibitor AZD8055 ameliorated DSS-induced colitis by increasing the functional activity of Treg cells and suppressing TH1 and TH17 cell response in vivo." (PMID 27128484, 2016). "It has been established that mammalian target of Rapamycin (mTOR) inhibitors have anti-inflammatory effects in models of experimental colitis." (PMID 27128484, 2016). "In addition, this study lacks mechanistic validation regarding the role of EB in regulating mTOR signaling and gut microbiota modulation in colitis improvement." (PMID 40077417, 2025). "Additionally, research shows increased P62, mTOR, and p-mTOR levels in experimental colitis, while LC3B and ATG16L1 levels are reduced." (PMID 40534879, 2025). "A study has confirmed that Baitouweng Decoction could elevate the levels of ZO-1, Occludin, which are beneficial to repairing colonic barrier in colitis mice by means of regulating AMPK/mTOR-mediated autophagy." (PMID 39351096, 2024). "Additionally, it protected mice from DSS-induced colitis by inhibiting inflammation through the PP2A-mediated PI3K/Akt/mTOR signaling pathway." (PMID 39201769, 2024). "mTOR suppression alleviates DSS-induced colitis by balancing the TH1/TH17/Treg profile." (PMID 39229575, 2024). "However, dapagliflozin decreased p-mTOR/mTOR in rat colitis model cells, suggesting that the inhibition of mTOR by AMPK is involved in AMPK-mediated enhancement of autophagy." (PMID 37055837, 2023). "Similarly, nicotine ameliorates the severity of DSS-induced colitis in a mouse model of UC by modulating AMPK/mTOR pathway-mediated autophagy and regulating apoptosis and proliferation." (PMID 37168865, 2023). "Importantly, mTOR deletion can reverse the more severe symptoms of acute colitis in TSC1cKO mice, as shown by significantly extended survival time, decreased macroscopic scores, and longer colon length in TSC1/mTORcKO mice compared with TSC1cKO mice." (PMID 36465179, 2022). "But a recent study reported that hypoxia may ameliorates inflammation of the colitis by modulating autophagy and mammalian target of rapamycin (mTOR)/NLRP3 pathway." (PMID 34666625, 2021).
colitis (continued). "In summary, we demonstrated that the deletion of mTOR in ILC3s reduced the release of inflammatory cytokines and the recruitment of neutrophils which correlated with limited tissue damage in an experimental model of colitis." (PMID 34341503, 2021). "Several studies have shown the effectiveness of mTOR inhibitors in colitis treatment." (PMID 33673488, 2021). "Interestingly, DCA attenuates Campylobacter jejuni-induced mouse colitis and mTOR signaling pathways in colonic tissues and immune cells." (PMID 34451506, 2021). "Additionally, sestrin 2 downregulates the mTOR activity, which is a strategy for treating colitis in humans due to its role in regulating cellular stress and inflammation." (PMID 33673488, 2021). "Another study demonstrated that liver and lymph node sinusoidal endothelial cell C-type lectin (LSECtin)-dependent apoptotic cell clearance by macrophages promotes resolution of inflammation and intestinal regeneration in a model of colitis via the activation of mammalian target of rapamycin (mTOR)." (PMID 34832962, 2021). "Using mice with mTOR deficiency in ILC3s on Rag2−/− background we show that IFN-γ release by ILCs and recruitment of IFN-γ-producing inflammatory neutrophils is impaired during colitis." (PMID 34341503, 2021). "In addition, the combination of Dex treatment with the blockade of mTOR signaling in intestinal epithelial cells significantly recovered the Dex-induced exacerbation of colitis." (PMID 32290362, 2020). "Therefore, mTOR signaling regulates intestinal epithelial cells or affects the function of immune cells in colitis." (PMID 32290362, 2020). "Hence, these results suggest that C. jejuni-induced colitis or colorectal tumorigenesis can be attenuated by inactivation of mTOR signaling using pharmacological interventions such as rapamycin or PI3K-γ inhibitors." (PMID 32231139, 2020). "It is reported that mTOR signaling pathway was activated in bacteria-induced colitis in mice." (PMID 31976001, 2019). "In addition, colonisation with the CDT producing Campylobacter jejuni has been shown to enhance tumour formation in the ApcMin/+ mouse model upon dextran sulfate sodium‐induced colitis, in a mechanistic target of rapamycin‐dependent manner (mTOR)." (PMID 31414579, 2019). "Inhibitors of mTOR signaling pathway are effective as anti-inflammatory drugs in treating colitis." (PMID 31976001, 2019). "In addition, overactivation of mTOR signaling through deletion of TSC1, an upstream negative regulator of mTOR, leads to reduced Treg suppressive activity in a mouse model of colitis." (PMID 29599783, 2018). "Using mouse models and in vitro 3D systems, we found that undifferentiated colonic epithelium produces high levels of innate immune cytokines and chemokines that drive inflammation, comparable to those proinflammatory molecules regulated by mTOR during colitis." (PMID 29596476, 2018). "By combining quantitative measures of epithelial hyperplasia and immune infiltration with multivariate analysis of inter- and intracellular signaling, we identified epithelial mammalian target of rapamycin (mTOR) signaling as a potential driver of inflammation in a mouse model of colitis." (PMID 29596476, 2018). "Indeed, our results showed that blocking mTOR phosphorylation (and activation) by rapamycin treatment concomitantly to AA diet consumption inhibited its boosting effect in colitis development." (PMID 29209321, 2017). "Moreover, in a mouse model of chemically induced colitis, the increased numbers of Treg cells and the concomitant suppression of mTOR signaling were reported in the intestinal tissue of mice treated with resveratrol." (PMID 28546852, 2017). "The active compounds in EB, particularly phlorotannins such as eckol and dieckol, may exert anti-inflammatory effects through PI3K/AKT/mTOR inhibition, NF-κB modulation, and gut microbiota regulation, highlighting its potential as an alternative or complementary treatment for colitis." (PMID 40077417, 2025).